INS (insulin)
Diseases named in the same sentence as INS in open-access papers (continued):
Sharing a sentence is not in itself a finding about the gene and the disease.
Insulin resistance (continued). "Insulin resistance, the state in which more insulin is required to maintain glucose homeostasis, is a common phenotype of PCOS patients and contributes to the pathogenesis of PCOS." (PMID 32334629, 2020). "β-cells compensate for insulin resistance by increasing insulin secretion, which consequently results in a reduction of glucose uptake in body cells and promotion of hyperinsulinemia." (PMID 33036127, 2020). "The failure to demonstrate an effect of genotype on fasting blood glucose and plasma insulin in either the preliminary or the main experiment was also unsupportive of an effect of genotype on insulin resistance." (PMID 32904155, 2020). "Insulin resistance (IR) classically refers to impaired sensitivity to insulin-mediated glucose disposal in muscles, body fat, and liver." (PMID 33287318, 2020). "In conclusion, despite the existence of insulin resistance, the jejunal expression of genes involved in insulin signalling was increased in MO-high-IR." (PMID 31936857, 2020). "Taken together, evidence suggests that inositol phosphates have pharmacological effects on increased insulin sensitivity, improved insulin resistance and other metabolic profiles, as well as decreased obesity and adiposity." (PMID 33139672, 2020). "It has been observed that these compounds can improve muscle vascular and peripheral insulin resistance, respectively, and an increase in insulin sensitivity in T2DM patients." (PMID 32258479, 2020). "In this study, 4-HIL intervention reduced weight gain, liver steatosis, and dyslipidemia; moreover, it increased systemic insulin sensitivity and improved insulin resistance in mice." (PMID 33551809, 2020). "The results from oral glucose-tolerance tests (OGTT) and insulin-tolerance tests (ITT) showed that NHP also markedly improved peripheral insulin resistance and glucose intolerance in HFD mice." (PMID 32759940, 2020). "Ultimately, corrected hyperglycaemia can also improve insulin sensitivity, since glucotoxicity by itself can lead to insulin resistance in healthy men and mice." (PMID 32472192, 2020). "The availability of both genetic and metabolomic data related to maternal insulin sensitivity during pregnancy allowed use of mediation analyses to define the potential role of metabolites in pregnancy-induced insulin resistance." (PMID 32556615, 2020). "Low insulin and insulin resistance observed in diabetic patients can contribute to decrease in glycogen levels." (PMID 32013797, 2020). "This pandemic is associated with markedly elevated blood glucose levels and a remarkable degree of insulin resistance, which suggests pancreatic islet β-cell dysfunction or apoptosis and insulin’s inability to dispose of glucose into cellular tissues." (PMID 33202960, 2020). "Increased phosphorylation of IRS-1 on residues Ser307 and Ser612 have been suggested to be responsible for the desensitization mechanisms of insulin-stimulated signal transduction which plays an important role in insulin resistance in obesity." (PMID 33344504, 2020). "HFD animals showed a 120% increase in plasma insulin levels, and CB denervation treated the insulin resistance and restored the normal insulin levels, suggesting the possible role of the CB in mediating insulin secretion." (PMID 32698380, 2020). "Some studies have shown that liver inflammation can impair insulin sensitivity, and selective depletion or inhibition of KCs by clodronate liposomes improves fasting hyperglycemia and insulin resistance in mice fed a high-fat diet (HFD)." (PMID 33692776, 2020). "Mitochondria are the major site of ROS production, and mitochondrial dysfunction will cause an increase in ROS production, and high levels of ROS impair insulin signaling pathways and induce skeletal muscle insulin resistance." (PMID 32082422, 2020).
Insulin resistance (continued). "Lipid-induced muscle insulin resistance (IR) is brought about primarily by impaired insulin signaling due to build-up of lipotoxic species and due to increased levels of circulating pro-inflammatory cytokines." (PMID 33101053, 2020). "LCN-2 expression was induced by agents promoting insulin resistance and was suppressed by insulin-sensitizing anti-diabetes drug." (PMID 32982804, 2020). "The adipokine profile is drastically altered in insulin resistance, with increased secretion of inflammatory adipokines, such as tumor necrosis factor α (TNFα), and decreased secretion of insulin-sensitizing adipokines, such as adiponectin." (PMID 32041341, 2020). "Type 2 diabetes is associated with obesity; while type 2 diabetics usually produce enough insulin, their cells cannot use it effectively, a process known as insulin resistance." (PMID 32604970, 2020). "Supplementation with Akkermansia can also improve insulin levels, insulin resistance, and total cholesterol levels in obese patients." (PMID 33551808, 2020). "Impaired response to either endogenous or exogenous insulin is a characteristics of insulin resistance." (PMID 32802365, 2020). "Insulin sensitization of these tissues, therefore, can potentially reduce and prevent systemic insulin resistance and its complications." (PMID 32041341, 2020). "In obese individuals with euglycaemia, peripheral insulin resistance is present but compensated by increased insulin secretion." (PMID 32458441, 2020). "In the liver and muscles, this process leads to the development of insulin resistance while in the pancreatic islands to disturbances in insulin secretion and apoptosis of β cells." (PMID 32397353, 2020). "Commonly, glucose intolerance is known for its hyperglycemia due to impaired glucose homeostasis, which is a result of impaired insulin secretion and/or increased insulin resistance." (PMID 33324347, 2020). "Liver-specific CerS6 null mice displayed a partial protection from diet induced obesity but a robust protection from glucose intolerance and insulin resistance explained by enhanced insulin signaling relative to wild type animals." (PMID 32849276, 2020). "Since glucose is the main stimulus for β cell insulin secretion, persistent hyperglycemia combined with peripheral insulin resistance induce β cells to increase their insulin secretion to compensate for high blood glucose levels in T2DM." (PMID 32960890, 2020). "The improvement of insulin action can be attributed to the effects of HO-1 attenuating the expression of insulin resistance mediators including TNF-α, IL-1β and increasing the levels of adiponectin." (PMID 32903449, 2020). "OP males were insulin resistant, but OP females exhibited only subtle signs of insulin resistance, as in humans." (PMID 32160920, 2020). "The secondary outcomes are differences in fasting insulin, homeostasis model assessment of insulin resistance, quantitative insulin sensitivity check index, and adverse events." (PMID 32221098, 2020). "Early stages of insulin resistance are characterized by increased insulin secretion from pancreatic β-cells for maintaining glucose homeostasis under overfeeding conditions." (PMID 32560216, 2020). "After 4 weeks of treatment, the fasting insulin levels of guinea pigs were measured, and the homeostatic model assessment of insulin resistance (HOMA-IR) score was estimated." (PMID 33150187, 2020). "Not surprisingly, as a result of the obesity epidemic, there is also an increasing incidence of T2D, a disease that is characterized by insulin resistance and a relative defect in insulin secretion." (PMID 32183037, 2020). "Insulin resistance and impaired insulin secretion are the two major abnormalities in the pathogenesis of T2DM." (PMID 32831068, 2020). "Oestrogens confer protection against insulin resistance through activation of the ERα pathway in insulin-sensitive tissues, as demonstrated in mouse models." (PMID 31754750, 2020).
Insulin resistance (continued). "Insulin resistance (IR) is defined by an increased insulin requirement of the organism to maintain normal blood glucose levels." (PMID 32887221, 2020). "A meta-analysis of eight clinical trials showed that administration of Ginseng, in comparison to the placebo, improves fasting glucose levels, postprandial insulin levels, and insulin resistance." (PMID 32317975, 2020). "Insulin resistance was assessed with the homeostasis model assessment index and the predicted insulin sensitivity index (PREDIM)." (PMID 33252690, 2020). "Animals fed with pomegranate juice, particularly those at the highest dose, showed a significant decrease in plasma glucose, along with an increase in the insulin levels and a decrease in Homeostatic Model Assessment for Insulin Resistance (HOMA-IR)." (PMID 33287432, 2020). "Diabetes is a metabolic disorder that is characterized by hyperglycemia and is due to defects in insulin secretion and/or insulin resistance (IR)." (PMID 32922365, 2020). "Insulin resistance is a condition in which the cellular responses to a given ambient insulin concentration are decreased relative to a normal control." (PMID 33139661, 2020). "Eventually, liver lipid overload and increased inflammation promote liver insulin resistance (IR), characterized by impaired insulin signaling." (PMID 33212990, 2020). "Insulin resistance (or decreased insulin sensitivity) is defined as the abnormal response of tissues to normal insulin levels." (PMID 33255783, 2020). "Factors increasing insulin resistance include high childbearing age, chronic low-grade inflammation due to obesity-induced lipid accumulation, and insulin-desensitizing effects of the hormonal products of the placenta." (PMID 32240385, 2020). "Insulin resistance leads to β-cell compensation, exhaustion, and consequently dysfunction of β-cell resulting in impaired insulin secretion." (PMID 33139672, 2020). "Other studies assessed the changes in the insulin and glucose levels, as well as homeostasis model assessment of insulin resistance (HOMA-IR) values following quercetin intake." (PMID 32005271, 2020). "The type 2 diabetes (T2D) is due to a progression of insulin secretary defect concomitantly with insulin resistance." (PMID 32365816, 2020). "The absence of insulin production and release in type 1 diabetes (T1D) and the poor action of insulin on target cells (insulin resistance) in type 2 diabetes (T2D) result in hyperglycemia." (PMID 33536868, 2020). "The response of β-cells to insulin resistance is to increase insulin secretion to maintain normal glucose levels, resulting in hyperinsulinemia." (PMID 31941993, 2020). "Adaptation ensure the maintenance of constant FFA andtriglyceride blood levels, but led to the appearance of signsof insulin resistance (decreased insulin sensitivity, glucosetolerance, and increased TG levels in the liver) in males andfemales." (PMID 35087997, 2020). "In conclusion, LBP reduced glucose levels and insulin resistance, increased insulin sensitivity and testosterone levels, and inhibited oxidative stress damage as well as pathological damage in the testes of obese mice." (PMID 32528287, 2020). "The term “insulin resistance” indicates that insulin-responsive tissues such as the liver, adipose tissue, and skeletal muscle reduce insulin-mediated glucose uptake, contributing to hyperglycemia." (PMID 32582032, 2020). "Patients with insulinoma that exhibit significantly elevated blood insulin levels have insulin resistance." (PMID 32230718, 2020). "Previous population-based studies on OSA and glucose metabolism have shown OSA to be associated with decreased insulin sensitivity derived from OGTT, insulin resistance, and impaired glucose tolerance, increasing HbA1c, and prediabetes." (PMID 32562183, 2020).
Insulin resistance (continued). "Increased acetic acid production from an altered gut microbiome exacerbates insulin resistance by activating the parasympathetic nervous system to promote glucose-stimulated insulin secretion and ghrelin secretion in obese rats." (PMID 32326255, 2020). "The Botnia study demonstrated that those with IFG were more insulin resistant, evidenced by significantly higher HOMA IR (Homeostatic Model Assessment of Insulin Resistance) and fasting insulin level." (PMID 32987806, 2020). "Both prediabetes and T2DM are characterized by poor response to insulin stimulation (i.e., insulin resistance) leading to inefficient glucose uptake and metabolism in insulin-sensitive tissues." (PMID 31329250, 2020). "In HFD-induced obese mice these peptides improved obesity and insulin resistance, pointing out that the obesogenic and insulin-resistant effect of EPO is intimately related to its hematopoietic effect." (PMID 32752277, 2020). "SIRT1 protects against inflammation and TNFA induced insulin resistance, whilst also promotes glucose uptake and insulin signaling in murine adipocytes." (PMID 33207733, 2020). "In diabetic patients, an increase in insulin secretion compensates for insulin resistance that leads to the decrease of the insulin-secreting cell activity resulting in decreased glucose tolerance." (PMID 32831835, 2020). "The decreased plasma MaR1 strongly associated with obesity, impaired glucose and lipid metabolism, reduced first-phase of glucose-stimulated insulin secretion, and enhanced insulin resistance." (PMID 32377160, 2020). "Insulin resistance was accompanied by unaltered proximal insulin signaling as reflected by Akt phosphorylation in skeletal muscle." (PMID 32053588, 2020). "That provides a rationale to investigate an insulin effect, isolated or combined to glucose and insulin resistance, on glucose transport proteins, mainly on their function." (PMID 32377524, 2020). "This direct testosterone infusion into the fetus also increase insulin secretion after a glucose load at 11 months old of age, indicating a fetal programmed hyperinsulinemia, which is likely to be an end result of insulin resistance." (PMID 31941959, 2020). "Skeletal muscle is one of the major target organs of insulin-mediated glucose uptake, metabolism and utilization, and it is the earliest and most important site of insulin resistance." (PMID 32859686, 2020). "This would confirm an increase in insulin resistance in jejunum from those morbidly obese subjects with high systemic insulin resistance." (PMID 31936857, 2020). "The results demonstrate a significant difference in mean values of fetuin-A, lipid profile, glucose, insulin and Homoeostasis Model Assessment of Insulin resistance (HOMA-IR) in type-II diabetics when compared to normal healthy individuals (p<0.01)." (PMID 32063933, 2020). "Regarding insulin and insulin resistance, insulin was declined in diabetic and diabetic obese patients compared to control group." (PMID 32544194, 2020). "While acute increases in insulin are important for maintaining blood glucose homeostasis, chronic insulin elevation, or chronic hyperinsulinemia, can lead to insulin resistance." (PMID 33345777, 2020). "Insulin resistance and impaired insulin absorption from subcutaneous space due to dermal tension and stiffness in SPS was reported in a patient with T2D." (PMID 32982980, 2020). "Pairwise meta-analysis and network meta-analysis were used to compare and rank the effects of nutritional strategies for the improvement of fasting plasma glucose (FPG), serum insulin, and homeostasis model assessment-insulin resistance (HOMA-IR)." (PMID 32185236, 2020). "Insulin resistance can furthermore be subdivided based on two distinct features: insulin sensitivity and insulin responsiveness." (PMID 32823892, 2020).
Insulin resistance (continued). "One of the possible mechanisms for explaining the association between abnormal PAPP-A and GDM is the decreased IGF, which leads to increased insulin, glucose clearance, and insulin resistance." (PMID 32500016, 2020). "It suggests a more improved insulin resistance, and thus, the lower dosage of insulin has a larger effect on glucose control and led to hypoglycemia." (PMID 32149152, 2020). "The study participants also demonstrated elevated insulin levels and the homeostatic model assessment of Insulin Resistance (HOMA-IR)." (PMID 32326589, 2020). "Saturated fatty acids and ceramide, associated with obesity and nutrient overload, can also trigger NLRP3 inflammasome to produce IL-1β that acts on the liver and impairs the activity of liver insulin, contributing to insulin resistance." (PMID 33113859, 2020). "In the state of insulin resistance, insulin inhibits the hydrolysis of TGs, and the excessive release of FFAs from the adipose tissue is absorbed by the hepatocytes and accelerates the synthesis of TGs." (PMID 32963741, 2020). "Insulin resistance with insufficient insulin secretion compensation is still common phenomenon during long-term postpartum." (PMID 32184821, 2020). "The delayed effects of the administered insulin on glucose levels in blood suggested the presence of insulin resistance." (PMID 32214195, 2020). "Insulin resistance is defined as inability of hormone insulin signals in tissues or cells to increase glucose uptake and utilization." (PMID 32082261, 2020). "PTH also has been reported to down-regulate insulin intracellular signaling, resulting in an increase in peripheral insulin resistance, and is also inversely correlated with insulin sensitivity." (PMID 33207657, 2020). "In C3H-Chr 11NSY mice, sucrose administration for 10 weeks deteriorated hyperglycemia, insulin resistance, and impaired insulin secretion, which is comparable to NSY mice with sucrose." (PMID 32703163, 2020). "Cell models of adipocyte lipid atrophy by oleic acid and palmitate, and a model of insulin resistance by high glucose-high insulin (HGHI) treatment were established." (PMID 32214011, 2020). "IMTG degradation leads to abnormal accumulation of DAG and ceramide, resulting in excessive activity of atypical PKC, and inhibiting insulin signaling to induce insulin resistance." (PMID 32178449, 2020). "Further investigations are required to reveal if modulating the expression, activity, or localization of proteins in the MAM interface has an impact on insulin action and if these strategies can be applied to the treatment of insulin resistance and T2DM." (PMID 33195204, 2020). "Attenuated insulin signalling can also result from changes in insulin resistance and/or post‐receptor signalling." (PMID 32940423, 2020). "Engaging these two TLRs gives rise to chronic inflammation and insulin resistance through direct interference with insulin signaling." (PMID 32140136, 2020). "It resulted in a dose-dependent improvement of glucose tolerance, insulin sensitivity, lower body weight, decreased fat mass, and a complete reversal of high-fat diet-induced insulin resistance." (PMID 32872317, 2020). "In adipocytes and peripheral tissue, the high level of TNF-α from the macrophages of tissues induces insulin resistance by altering insulin signalling via serine phosphorylation, again, leading to the development of T2DM." (PMID 33299532, 2020). "Genetically determined insulin resistance specifically renders pancreatic fat deleterious for insulin secretion." (PMID 32725157, 2020). "This increase in FFA in combination with insulin resistance and decreased insulin signaling increases chylomicron secretion." (PMID 33291273, 2020). "The big breakfast group also had a greater decrease in fasting glucose, insulin, and insulin resistance, while reporting greater satiety, lower hunger, and having concordantly lower ghrelin levels." (PMID 32363197, 2020).